DUSP16 (dual specificity phosphatase 16)
Diseases named in the same sentence as DUSP16 in open-access papers (continued):
Sharing a sentence is not in itself a finding about the gene and the disease.
cancer (10 papers, 2010 to 2025). A tumor composed of atypical neoplastic, often pleomorphic cells that invade other tissues. "Here, the authors show that dual-specificity phosphatase 16 (DUSP16) expression is associated with chemoresistance in several types of cancer through impairing mitochondria-associated apoptosis." (PMID 33863904, 2021). "Overall, these results suggest that DUSP16 promotes resistance to chemotherapy drugs in cancer cells through prevention of BAX accumulation in the mitochondria and the activation of mitochondria cell death pathway, thereby suppressing apoptosis." (PMID 33863904, 2021). "This study therefore identifies DUSP16 as a prognostic marker for the efficacy of chemotherapy, and as a therapeutic target for overcoming chemoresistance in cancer." (PMID 33863904, 2021). "Cancer cells expressing higher DUSP16 are intrinsically more resistant to chemotherapy-induced cell death than cells with lower DUSP16 expression." (PMID 33863904, 2021). "Overexpression of DUSP16 in cancer cells leads to increased resistance to cell death upon chemotherapy treatment." (PMID 33863904, 2021). "Subsequent investigations revealed that the upregulation of DUSP16 in neoplastic cells conferred augmented resistance to apoptotic cell death following chemotherapy, whereas the downregulation of DUSP16 enhanced the sensitivity of cancer cells toward treatment." (PMID 38674085, 2024). "Therefore, JNK and p38 activation by chemotherapeutic compounds promotes cell apoptosis, and DUSP16 expression promotes resistance to these compounds in cancers by inhibiting both JNK and p38." (PMID 33863904, 2021). "In contrast, knockdown of DUSP16 in cancer cells increases their sensitivity to treatment." (PMID 33863904, 2021). "To explore if DUSP16 commonly regulates cancer cell sensitivity to chemotherapeutic agents through JNK and p38, we treated vector- or DUSP16-expressing HCT116, HK-1, Nugc3, and MDA-MB-231 cells with 5-Fluorouracil (5-FU) or epirubicin to examine cell apoptosis." (PMID 33863904, 2021). "Therefore, DUSP16 regulates JNK/p38-BAX signaling pathway to mediated resistance to various chemotherapeutic agents in cancer." (PMID 33863904, 2021). "It remains to be determined, however, whether DUSP16 is downregulated in other cancers by genetic or other mechanisms." (PMID 20551953, 2010). "To test whether DUSP16 regulates the response of cancer cells to other chemotherapy drugs, we treated NPC cells HK-1 and C666-1 with carboplatin which is used for treating NPC62, and CRC cells DLD-1 and HCT116 with oxaliplatin which is used in the management of metastatic colorectal cancer." (PMID 33863904, 2021). "However, whether DUSP16 regulates cancer sensitivity to platinum-based therapies and other drugs is unclear." (PMID 33863904, 2021). "The important function of DUSP16 in mediating sensitivity to chemotherapy in various types of cancers suggests that it could serve as a predictive marker for stratifying responsive patients, and as a target for the development of therapies to improve the effectiveness of chemotherapy." (PMID 33863904, 2021). "In addition, the role of DUSP16 in the response of cancers to chemotherapeutic agents identified in this study suggests that DUSP16 could be a marker for predicting the efficacy of chemotherapy, and also a target for the development of therapies to improve treatment efficacy." (PMID 33863904, 2021). "Together, these results demonstrate that DUSP16 directly interacts with and inhibits the activation of both JNK and p38, thereby regulating the response to chemotherapy drugs in various types of cancer cells." (PMID 33863904, 2021). "It is plausible that DUSP16, whose expression is induced by chemotherapeutic agents, targets both JNK and p38 to regulate cancer cell response, and therefore, might be an important target for enhancing the efficacy of chemotherapy." (PMID 33863904, 2021).
cancer (continued). "Our data suggest that ERK activation in responses to chemotherapeutic drugs may differ depending on the type of cancer cells, and ERK is not likely to be involved in the DUSP16-mediated resistance commonly observed in various types of cancer cells." (PMID 33863904, 2021).
infection (3 papers, 2022 to 2023). The state of being infected such as from the introduction of a foreign agent such as serum, vaccine, antigenic substance or organism. "Similar, in the chicken, DUSP1, DUSP5, DUSP7, DUSP10, DUSP15, and DUSP16 were significantly downregulated in response to infection." (PMID 36683094, 2023).
DUSP16 also shares sentences with these, for which no sentence is quoted: acute myeloid leukemia (3 papers); Alzheimer disease (3); asthma (2); neurodevelopmental disorder (2); obstructive hydrocephalus (2); acute lymphoblastic leukemia (1); Aqueductal stenosis (1); B-cell neoplasm (1); Burkitt lymphoma (1); Cerebral ischemia (1); cervical cancer (1); colitis (1); colorectal cancer (1); diabetes (1); glioblastoma (1); head and neck squamous cell carcinoma (1); inflammatory bowel disease (1); ischemia (1); lung injury (1); lupus (1); malignant melanoma (1); memory impairment (1); nasopharyngeal carcinoma (1); oral squamous cell carcinomas (1); psoriasis (1); rheumatoid arthritis (1); squamous cell carcinoma (1); stenosis (1); viral infection (1).